MIR5589 (microRNA 5589)
Synonyms: hsa-mir-5589
Gene: MicroRNA gene on chromosome 19 (10,038,354 to 10,038,413, forward strand). Ensembl gene ENSG00000266204.
Homologues: Orthologues: chimpanzee MIR5589 (100% identical).